STAT3 (signal transducer and activator of transcription 3)
Diseases named in the same sentence as STAT3 in open-access papers (continued):
Sharing a sentence is not in itself a finding about the gene and the disease.
multiple myeloma (continued). "Several studies have demonstrated that inhibition of the IL6R/STAT3 pathway with anti-IL6, IL6R antagonists, or JAK-inhibitors induced apoptosis of human myeloma cell lines in vitro and enhanced the antitumor activity of other anti-myeloma drugs in vivo, attenuating chemoresistance." (PMID 34205916, 2021). "In addition, the proliferation of myeloma cells was potently inhibited in vitro and in vivo secondary to the inhibition of phosphorylated FGFR3, phosphorylation of Jak2 and Stat3 and Cyclin D2 by AZD1480." (PMID 34680353, 2021). "In myeloma, SHP-2 can reduce the phosphorylation of STAT3 and thus suppress its activation." (PMID 34195079, 2021). "We previously reported that the STAT3 activity is essential for the cell viability of two myeloma cell lines (U266 and RPMI8226) in 3D but not in conventional culture." (PMID 34201211, 2021). "Myeloma cells rely on the pleiotropic cytokine IL-6, which activates the JAK/STAT3 pathway." (PMID 31963765, 2020). "It should be noted that while each myeloma cell line exhibited distinctly different basal levels of STAT3 activation; this did not correlate with sensitivity to PDX nor MTX." (PMID 32405334, 2020). "It explicitly restrained both constitutive and inducible STAT3 activation at tyrosine 705, but not at serine 727, in human multiple myeloma cells." (PMID 32545187, 2020). "While upregulation of anti-apoptotic genes is important for myeloma cell survival, it does not fully account for the survival benefits conferred by IL-6 through STAT3." (PMID 31130718, 2019). "Numerous reports state that IL-6 plays an essential role in the malignant progression of multiple myeloma, whereby the engagement of IL-6 with specific surface cytokine receptors activates JAK and subsequently triggers the activation of STAT3 signaling pathways." (PMID 31402861, 2019). "In multiple myeloma-derived BMMSCs, it has recently been reported that miR-21 directly targeted to reduce OPG and indirectly promoted RANKL by targeting the signal transducer and activator of transcription 3 (STAT3) pathway, suggesting inhibition of osteoclastogenesis by miR-2110." (PMID 28240263, 2017). "It has been established that interleukin-6 (IL-6) is the most important survival and growth factor in myeloma cells and regulated at least 3 pathways, namely JAK2/STAT3, MAPK/ERK, and PI3K/AKT, thus targeting IL-6-mediated signaling pathways is a promosing therapeutic strategy in MM." (PMID 25865044, 2015). "Our previous report also shows that inhibition of Lyn activity significantly blocks the proliferation-induced by IL-6 in CD45+ myeloma cells, but does not affect either STAT3 or ERK activation." (PMID 25781885, 2015). "We further investigate whether nuclear localization of STAT3 is different between CD45+ and CD45- myeloma cells." (PMID 25781885, 2015). "In the case of co-culture with MSC, myeloma cells survive independent of the IL-6/gp130/STAT3 pathway suggesting that other pro-myeloma factors, such as CCN1, are provided by the stromal tumor microenvironment." (PMID 24965524, 2014). "One key consequence of JAK-STAT activation is overactivity of STAT3, a STAT family transcription factor which results in high expression of the antiapoptotic protein Bcl-xL, a protein correlated to chemoresistance in myeloma patients." (PMID 24803933, 2014). "An additional impact on STAT3 phosphorylation as observed in a myeloma cell line has not been detected in human B cells." (PMID 22571761, 2012). "In a recent report, AZD1480 blocked both JAK/STAT3 and FGFR3 signaling in myeloma cells." (PMID 23056499, 2012).
multiple myeloma (continued). "Although there are some cell type-specific restrictions to its effects, pimozide readily inhibits STAT3 tyrosine phosphorylation in a number of systems, including the multiple myeloma cell lines INA6 and U266 (data not shown)." (PMID 21680956, 2011). "Targeting STAT3 and MEK/ERK/BCL2 activity by specific inhibitors resulted in significant MM cell death and growth inhibition and their combinations had a synergistic cytotoxic effect on myeloma cells." (PMID 20930946, 2010). "Since the STAT3 and MEK/ERK signaling pathways were both involved in CKS1B-induced myeloma cell growth and survival, a combined targeting of these signaling pathways might induce synergistic cytotoxicity in myeloma cells." (PMID 20930946, 2010). "We identified STAT3 and MEK/ERK/BCL2 as CKS1B-downstream signaling pathways; and thereby provided targets for the development of new therapeutic approaches for CKS1B over-expressing myeloma and other tumor malignancies." (PMID 20930946, 2010). "To demonstrate that the avicin-mediated regulation of Stat3 was not restricted to U266 cells, we studied some other multiple myeloma cell lines." (PMID 19440292, 2009). "In multiple-myeloma cell cultures, NAZ concentration of 3 μM could inhibit STAT3 activity." (PMID 36297506, 2022). "Therefore, we thought that it could be one of the effective treatment protocols if the activated STAT3 and JAK2 signals in multiple myeloma can be controlled with radotinib." (PMID 35503759, 2022). "Because we recently found that STAT3 induces the expression of GLI1 in chronic lymphocytic leukemia (CLL) and multiple myeloma cells, and because the JAK-STAT pathway is constitutively activated in MF, we wondered whether STAT3upregulates GLI1 in MF fibrocytes." (PMID 35595725, 2022). "For example, in multiple myeloma, paracrine cytokine stimulation occurs as a result of myeloma cells interacting with bone marrow, resulting in increased production of IL-6, which activates JAK2 and STAT3, all of which are required for proliferation and survival." (PMID 36008987, 2022). "Moreover decreased glycolysis also reduced the phosphorylation of ERK1/2 and STAT3, thus affecting glucose uptake, lactate production and myeloma cell proliferation, without any changes in the total protein levels of ERK1/2 and STAT3." (PMID 32626538, 2020). "Additionally, work on myeloma cell lines showed that B7-H3 activates STAT3, subsequently promoting cell proliferation, by encouraging the degradation of SOCS3, a known inhibitor of STAT3 phosphorylation." (PMID 32992699, 2020). "Similarly, our previous study observed that the pretreatment of myeloma cells with JSI-124 and bortezomib can recover DC functions through the up-regulation of HSP90 and down-regulation of p-STAT3 and inhibitory cytokines, and that these DCs can potently generate myeloma-specific CTLs." (PMID 28512265, 2017). "Moreover, we found in a multiple myeloma mouse model that exosomes derived from bone marrow stromal cells or multiple myeloma cells themselves could activate both the STAT1 and STAT3 pathway leading to expansion and increased suppressive activity of the MDSCs." (PMID 27029037, 2016). "Our study demonstrate that up-regulated leptin could stimulate proliferation and reduce the anti-tumor effect of chemotherapy in multiple myeloma possibly via activating AKT and STAT3 pathways, and leptin might be one of the potential therapeutic targets for treating myeloma." (PMID 27863383, 2016). "Taken together, our study demonstrated that up-regulated leptin could stimulate proliferation of myeloma and reduce the anti-tumor effect of chemotherapy possibly via activating AKT and STAT3 pathways, and leptin might be one of the potential therapeutic targets for treating myeloma." (PMID 27863383, 2016).
multiple myeloma (continued). "STAT3 protein binding at the EZH2 promoter was significantly increased in SGC7901 cells, and was increased 6.18-fold with IL-6 stimulation, which is consistent with the results of studies showing that EZH2 protein expression is induced by IL-6 in multiple myeloma cell lines." (PMID 27938379, 2016). "Importantly, stimulation of myeloma cells with IL-6 increased the proportion of CD45RO in the raft fractions, where CD45RO formed a complex with IL-6R, gp130, STAT3 and PKC, that could potentiate the activation of STAT3, PKC and downstream NF-κB." (PMID 25781885, 2015). "Nuclear receptors, including ER, are negative modulators of STAT3 in multiple myeloma cells." (PMID 24913037, 2014). "While IL-6 signals via at least 3 pathways in multiple myeloma, namely STAT3, ERK1/2, and AKT, we first biologically validated the impact of YM155 on IL-6/STAT3-signalling, finding a concentration-dependent decrease of phospho-STAT3 in both cell lines after 24 hours under normal growth conditions." (PMID 25296978, 2014). "Since the combination of decursin- and doxorubicin-induced apoptosis in three multiple myeloma cells regardless of STAT3 existence, we examined another signaling pathway relevant to synergistic antitumor effect of combination of decursin and doxorubicin in three multiple myeloma cells." (PMID 23818927, 2013). "To test the hypothesis that Stat3 activates ROR1, we used the multiple myeloma cell line MM1." (PMID 20686606, 2010). "Similarly, a study in multiple myeloma (MM) demonstrated that a combination of AT9283 with Lenalidomide (orally active immunomodulator) led to significant synergistic cytotoxicity in preclinical models, and the proposed mechanism of action was blocking Stat3 phosphorylation." (PMID 34680353, 2021). "In myeloma cells, PF4 is identified have a negative effect on the angiogenesis and growth and a positive effect on the apoptosis via downregulating signal transducers and activators of transcription(STAT3) and phosphorylation of STAT3 whichis associated with SOCS3." (PMID 29383198, 2017). "Leptin stimulated the growth of both myeloma cells via increasing AKT and STAT3 phosphorylation, without changing expression of AKT and STAT3." (PMID 27863383, 2016). "Specially, other groups demonstrate the inhibition of ERK without interference with phosphorylation of STAT3, as well as the inhibition of arsenic trioxide on IL-6-induced STAT3 but not ERK activation in myeloma cells." (PMID 25781885, 2015). "CCN1-dependent signaling pathways were not involved mechanistically in this pro-myeloma effect as no alterations in phosphorylated p38, ERK1/2, and STAT3 by CCN1 treatment of INA-6 cells was observed." (PMID 24965524, 2014). "Western blots detected increased levels of p-STAT3, p-MEK1/2 and p-ERK1/2 in p27Kip1-transfected myeloma cells with no remarkable effect on p-BCL2 levels compared with WT and EV controls." (PMID 20930946, 2010). "Furthermore, we report for the first time that piperlongumine inhibited the activation of STAT3 by directly binding to Cys712 near the SH2 domain; piperlongumine had no anti-myeloma effects in cells with mutant STAT3 (C712A)." (PMID 27634873, 2016). "Interestingly, the phosphorylation level of STAT3 but not STAT1 in CD45+ cells was significantly higher compared to that of CD45- cells, while the phosphorylation level of ERK in CD45+ myeloma cells was relatively low." (PMID 25781885, 2015). "However, it has little effect on myeloma cell lines lacking STAT3 activation, or on peripheral blood mononuclear cells (PBMC) harvested from healthy donors, which also lack STAT3 activation." (PMID 21680956, 2011).
osteosarcoma (322 papers, 2007 to 2026). A usually aggressive malignant bone-forming mesenchymal neoplasm, predominantly affecting adolescents and young adults. "LRP8 has been implicated in various malignancies, with studies showing that its overexpression increases phospho-STAT3 (p-STAT3) levels, a marker associated with metastasis and poorer outcomes in osteosarcoma." (PMID 40506610, 2025). "As a transcription factor that regulates apoptosis, proliferation, and immune evasion, the activation of STAT3 has been implicated in the aggressiveness of osteosarcoma and its resistance to therapy." (PMID 40625361, 2025). "The introduction of additional ferroptosis inducers or STAT3 inhibitors has been demonstrated to increase the susceptibility of osteosarcoma cells to cisplatin, offering a potential approach to treating drug‐resistant osteosarcoma." (PMID 40475985, 2025). "Meanwhile, FANCD2 knockdown predisposed osteosarcoma cells to ferroptosis by regulating the JAK2/STAT3 pathway." (PMID 36814203, 2023). "lncRNA BLACAT1 (Bladder cancer associated transcript 1) interacts with STAT3 and regulates the phosphorylation of STAT3 and contributes to the proliferation and migration of osteosarcoma cells." (PMID 35755302, 2022). "Huang and colleagues demonstrated an augmented expression of circHIPK3 in osteosarcoma cells, which downregulated miR-637, relieved its negative regulation on STAT3, and caused osteosarcoma cell metastasis." (PMID 36292157, 2022). "STAT3 is both a proto-oncogene and molecular target of known oncogenes implicated in the development of osteosarcoma." (PMID 36151091, 2022). "MAP kinase kinase 7 (MKK7) activates c‐Jun N‐terminal kinase (JNK), which is linked to STAT3 phosphorylation, and it can be repressed by miR‐125b in osteosarcoma." (PMID 33332677, 2021). "With focus on the concomitant activation of EGFR and STAT3 as determinants of osteosarcoma progression, we investigated the mechanisms underlying the anticancer effects of SC, a cantharidin analogue, alone and in combination with the EGFR inhibitor erlotinib." (PMID 31422383, 2019). "In this study, we investigated the antitumor effect of napabucasin (NP) (BBI608), an inhibitor of STAT3 on osteosarcoma in vitro and in vivo and studied the underlying molecular mechanism." (PMID 30286779, 2018). "In addition to mTOR, miR-199a-3p negatively regulates STAT3, another critical molecule implicated in Osteosarcoma pathogenesis." (PMID 40429954, 2025). "Notably, aberrant STAT3 activation has been observed in osteosarcoma patients and is linked to poor prognosis." (PMID 40975978, 2025). "A previous study showed that LGR4 could be up-regulated by Stat3 in human osteosarcoma cells, but reduced when Stat3 was deficient." (PMID 38292169, 2024). "Anomalous STAT3 activation in osteosarcoma cells has been linked to grim survival outcomes." (PMID 38140058, 2023). "Taken together, these findings demonstrate that NHWD-870, as an effective BET inhibitor, may be a potential candidate for osteosarcoma intervention linked to its STAT3 signaling inhibitory activity." (PMID 34168981, 2021). "Given that PTPRD inactivation may increase STAT3 activity, the use of STAT3 inhibitors may have relevance in the treatment of osteosarcomas with PTPRD mutations." (PMID 25126591, 2014). "To examine whether targeting STAT3 by LLL12 inhibits not only VEGF but also other critical angiogenic factors in osteosarcoma tumors, we examined the levels of 55 angiogenesis-associate proteins using a human angiogenesis array." (PMID 22530037, 2012). "Indeed, osteosarcoma is a highly aggressive malignancy with very limited pharmacological therapeutic options, and the activation of the STAT3 pathway is associated with tumor progression, cell survival, drug resistance, and adverse prognosis in this malignancy." (PMID 40732256, 2025). "Furthermore, STAT3 is overexpressed in osteosarcoma and associated with poor survival." (PMID 37197432, 2023).
osteosarcoma (continued). "In addition to STAT3 playing a pivotal role during mammalian development, immune responses, inflammation and hematopoiesis, it has been implicated in the onset and progression of human cancers, including osteosarcoma." (PMID 36151091, 2022). "This is achieved through regulation of the VEGFR2/STAT3/Bcl-2 signal pathway in both in vivo and in vitro studies of osteosarcoma." (PMID 41438689, 2026). "Inhibition of the STAT3/SOX2 signaling axis dramatically reduced the DUSP3 downregulation-promoting effects on osteosarcoma cell proliferation, migration, and invasion." (PMID 39744427, 2025). "LCP1 has been reported to promote proliferation and metastasis in osteosarcoma cells via the JAK2/STAT3 pathway." (PMID 41044643, 2025). "This has led to preclinical studies exploring STAT3 inhibitors as a potential therapeutic approach in osteosarcoma." (PMID 40109854, 2025). "For instance, a study demonstrated that the STAT3 inhibitor cryptotanshinone effectively reduced tumor progression and improved survival rates in osteosarcoma models by inhibiting IL-6 signaling." (PMID 40909292, 2025). "In anaplastic thyroid carcinoma and osteosarcoma, high SIGLEC-15 expression likewise predicted worse outcomes and was linked to the activation of pro-tumor pathways (STAT3/BCL-2)." (PMID 40943560, 2025). "Meanwhile, coptisine specifically blocks the phosphorylation of STAT3 at the Tyr705 residue, synergistically suppressing capillary-like network formation driven by osteosarcoma cells, ultimately effectively inhibiting VM in osteosarcoma MG63 cells." (PMID 41019994, 2025). "Previous studies have shown that miR-26b-5p targets methionine adenosyltransferase 2A (MAT2A), leading to reduced GSH levels and promoting ferroptosis by blocking the STAT3/SLC7A11 pathway in osteosarcoma." (PMID 40403492, 2025). "Sunitinib, a VEGFR-TKI, inhibits PD-L1 expression in osteosarcoma by targeting STAT3 and remodels the immune system in tumor-bearing mice." (PMID 41394850, 2025). "Co-immunoprecipitation confirmed that CDK9 interacts with both GBP1 and STAT3 in osteosarcoma cells." (PMID 40975978, 2025). "The suppression of STAT3 by miR-199a-3p leads to reduced migratory and invasive capabilities of Osteosarcoma cells." (PMID 40429954, 2025). "Apatinib inhibits migration and invasion as well as PD-L1 expression in osteosarcoma by targeting signal transducer and activator of transcription 3 (STAT3)." (PMID 41394850, 2025). "M2-polarized macrophages can enhance the metastatic potential of osteosarcoma cells by activating Janus kinase (JAK2)/signal transducer and activator of transcription 3 (STAT3) signaling." (PMID 40005151, 2025). "Pimozide suppresses osteosarcoma cell proliferation and stemness via phosphorylating STAT3 and STAT5, according to a pharmacological investigation." (PMID 39744427, 2025). "Recent research has shown that targeting the IL-6/JAK/STAT3 signaling pathway can significantly inhibit osteosarcoma growth and metastasis by reducing tumor self-seeding and enhancing antitumor immunity." (PMID 40909292, 2025). "Collectively, our results demonstrated that DUSP3 regulates the stemness of osteosarcoma cells through the EGFR/STAT3/SOX2 axis." (PMID 39744427, 2025). "It suppresses tumor angiogenesis and induces autophagy and apoptosis in osteosarcoma cells by inhibiting the downstream VEGFR2/STAT3/BCL-2 signaling pathway." (PMID 41395622, 2025). "In fact, overexpression of STAT3 is correlated with poor prognosis of multiple cancers along with osteosarcoma." (PMID 40529368, 2025). "As a result, miRNA-221 was suggested to elevate the P-gp and Bcl-2 expression by stimulating the STAT3 pathway to foster DOX resistance in osteosarcoma cells." (PMID 39679367, 2024). "It will promote the apoptosis and inhibit proliferation of human osteosarcoma cells through inhibiting the STAT3/c‐Myc signaling pathway." (PMID 38800967, 2024).